CDKN1C (cyclin dependent kinase inhibitor 1C)
Diseases named in the same sentence as CDKN1C in open-access papers (continued):
Sharing a sentence is not in itself a finding about the gene and the disease.
diabetes (11 papers, 2016 to 2025). "The cause for diabetes has been associated with increased expression of CDKN1C in the pancreatic B cells." (PMID 31976094, 2019). "Additionally, deletion of CDKN1C has been shown to improve human islet function and gain-of-function mutants are associated with diabetes development and hyperinsulinism." (PMID 40982369, 2025). "Expression of both KCNQ1 and CDKN1C demonstrated to exhibit temporal effects in fetal and adult human pancreas and islets emphasizing that the diabetes risk may be mediated in early development." (PMID 34276762, 2021). "It remains to be determined whether IMAGe patients also develop diabetes at a later stage in life; however, these findings suggest that mutation of CDKN1C alone may be sufficient to drive a monogenic form of diabetes." (PMID 33986727, 2021). "BWS children can display neonatal hypoglycemia and one recent study reported early onset diabetes in a family with a mutation in CDKN1C, all of which could suggest a metabolic function for CDKN1C in humans." (PMID 26963625, 2016). "Impairments in the CDKN1C gene have also been linked with the development of early-adulthood-onset diabetes and may provide a linkage between these 2 factors: IC2 hypomethylation at chromosome 11, as described in our patient, affects the expression of CDKN1C gene." (PMID 39027637, 2024). "In adults with IUGR, Cyclin-dependent kinase inhibitor 1C (CDKN1C), a cell proliferation regulator that affects pancreatic β cells, can have a mutation at chromosome 11p15, resulting in decreased fetal growth, growth deficiency, and the onset of diabetes at a young age." (PMID 36714657, 2022). "To support the DEGAS approach for identifying true markers of β-cell subpopulations or heterogeneity associated with diabetes, we selected DLK1 and CDKN1C as candidate genes for immunostaining in formalin-fixed paraffin-embedded (FFPE) human pancreas sections from ND and T2D donors." (PMID 40982369, 2025). "A SNP residing in KCNQ1 that is maternally associated with diabetes is a maternal eQTL of CDKN1C, not KCNQ1." (PMID 40502026, 2025). "Previous studies confirmed that CDKN1C played an important role in the neurogenesis, migration and morphology, of which overexpression could inhibit the proliferation of β-cells, leading to diabetes." (PMID 37700362, 2023). "The risk allele of rs163184 attenuates Sp3 binding, and therefore, enhances the transcriptional activity of cyclin-dependent kinase inhibitor 1C (CDKN1C), which inhibits human β cell proliferation and promotes diabetes." (PMID 33919522, 2021).
melanoma (10 papers, 2015 to 2025). A malignant, usually aggressive tumor composed of atypical, neoplastic melanocytes. "Nevertheless, a few other cases with pathogenic CDKN1C variants have been diagnosed in adulthood with BWSp and cancer: a mesoblastic nephroma in a 33-year-old male patient and a superficial spreading melanoma that was diagnosed in a 42-year-old female patient." (PMID 35954470, 2022). "Thus here we may suggest, that in the future study, a larger cohort of clinical samples should be included in the research to further determine the underlying mechanism of lncRNA GAS5, EZH2, and CDKN1C in melanoma." (PMID 32308561, 2020). "Following after, RT-qPCR and western blot analysis were employed to examine the expression of EZH2 and CDKN1C in 6 pairs of melanoma tissues and adjacent normal tissues." (PMID 32308561, 2020). "Taken together, these results revealed that miR-517a targets the regulation of CDKN1C-mediated JNK signaling pathway in melanoma." (PMID 32015692, 2020). "The correlation of lncRNA GAS5, EZH2, and CDKN1C with survival rate of melanoma patients was analyzed." (PMID 32308561, 2020). "Silencing lncRNA GAS5 accelerated the EZH2 expression as well as H3K27 trimethylation to suppress the CDKN1C transcription and oxidative stress in melanoma." (PMID 32308561, 2020). "Downregulation of miR-517a inactivated the JNK signaling pathway while upregulating CDKN1C expression, leading to OS in melanoma." (PMID 32015692, 2020). "It was found that EZH2 presented significantly higher expression in melanoma tissues than in adjacent normal tissues, while the expression of CDKN1C in melanoma tissues was lower than that in adjacent normal tissues (p < 0.05)." (PMID 32308561, 2020). "In conclusion, we show here that miR-517a is activated in melanoma and that it directly targets CDKN1C." (PMID 32015692, 2020). "It was demonstrated that the inhibition of miR-517a contributes to OS via inactivation of the JNK signaling pathway by upregulating CDKN1C, in melanoma cells." (PMID 32015692, 2020). "In consent with these findings, our results showed that inhibition of CDKN1C by EZH2 leads to a significant increase in melanoma cell viability and a decrease in oxidative stress and apoptosis due to catalyzing the H3K27 trimethylation." (PMID 32308561, 2020). "The evidence provided by our study highlighted the involvement of lncRNA GAS5 in the translational suppression of EZH2 as well as the upregulation of CDKN1C, resulting in the promotion of melanoma cell apoptosis and oxidative stress." (PMID 32308561, 2020). "Since overexpression of EZH2 accelerated H3K27 trimethylation leading to CDKN1C silencing and oxidative stress inhibition in melanoma." (PMID 32308561, 2020). "Initially, our data demonstrated that miR-517a was upregulated, while CDKN1C was downregulated in melanoma cells." (PMID 32015692, 2020). "Our work thus identifies the potential role of miR-517a/CDKN1C/JNK axis in the treatment of OS in melanoma." (PMID 32015692, 2020). "Until now, only a few studies focused on the roles of miR-517a and the JNK signaling pathway via targeting of CDKN1C in OS in melanoma." (PMID 32015692, 2020). "High expression of EZH2 and poor expression of lncRNA GAS5 and CDKN1C was observed in melanoma tissues and found to be correlated with the reduction in survival expectancy of melanoma patients." (PMID 32308561, 2020). "It has also been suggested that silencing miRNA-517a in melanoma patient samples results in the overexpression of CDKN1C (cyclin-dependent kinase inhibitor 1C) and suppression of the c-Jun N-terminal kinase (JNK)-mediated survival and proliferation pathway, leading to increased ROS." (PMID 39594467, 2024). "EZH2, as well as CDKN1C, have also been recognized as promising biomarkers for treating melanoma." (PMID 32308561, 2020).
melanoma (continued). "The DEGs that associated with other genes in this network are KIT, CDKN1C, and TYRP1, suggesting these three DEGs may affect melanoma, in which TYRP1 was both a DEG and a melanoma gene." (PMID 32015692, 2020). "Consequently, our findings demonstrate that the elevation of lncRNA GAS5 upregulates CDKN1C to suppress the viability of melanoma cells and induce cell apoptosis as well as oxidative stress by inhibiting EZH2 expression and H3K27 trimethylation." (PMID 32308561, 2020). "It has been shown that melanoma cells can utilize CDKN1C/P57 to regulate cell cycle arrest." (PMID 32015692, 2020). "Interestingly, the heat maps of the top 60 DEGs of melanoma gene expression microarray data GSE31909 and GSE35389-mRNA revealed that CDKN1C expression in melanoma cells was lower than that in normal melanocytes." (PMID 32015692, 2020). "This study proposed a potential therapeutic target lncRNA growth arrest-specific transcript 5 (GAS5) for melanoma, due to its crucial role in oxidative stress and apoptosis of melanoma cells by regulating the enhancer of zeste homolog 2 (EZH2)-mediated CDKN1C expression." (PMID 32308561, 2020). "Based on this above discussion, we hypothesized that lncRNA GAS5 acts as a suppressor in melanoma and its underlying mechanism could involve EZH2 and CDKN1C." (PMID 32308561, 2020). "Several studies have indicated that activation of the JNK signaling pathway is involved in melanoma, and CDKN1C is known to inhibit the JNK signaling pathway, suggesting that CDKN1C could modulate the JNK signaling pathway in melanoma." (PMID 32015692, 2020). "Another important finding of our study reported that the overexpression of EZH2 further accelerated the H3K27 trimethylation which suppress the oxidative stress as well as apoptosis in melanoma cell and stimulated the viability of melanoma cell via inhibition of CDKN1C." (PMID 32308561, 2020). "The conclusion could be reached that silenced EZH2 or overexpressed CDKN1C could block the cell viability of melanoma and accelerate oxidative stress and cell apoptosis of melanoma." (PMID 32308561, 2020). "In subsequent experiments, we further identified that lncRNA GAS5 could upregulate CDKN1C to accelerate oxidative stress and apoptosis of melanoma cells and inhibit its viability by blocking EZH2 and H3K27 trimethylation." (PMID 32308561, 2020). "Thus, the present study assessed the functions of lncRNA GAS5, EZH2, and CDKN1C in the oxidative stress of melanoma cells." (PMID 32308561, 2020). "Overexpression of lncRNA GAS5 or CDKN1C or EZH2 knockdown could inhibit cell viability but enhance melanoma cell apoptosis and oxidative stress." (PMID 32308561, 2020). "MiR-517a was upregulated, while CDKN1C was downregulated in melanoma tissues and cells." (PMID 32015692, 2020). "Therefore, this study was aimed to investigate the possible mechanisms of miR-517a in melanoma through CDKN1C and the JNK signaling pathway." (PMID 32015692, 2020). "However, our data indicate that in melanoma cells deficient in CDKN1A/P21, the alternative CDK inhibitor CDKN1C/P57 is expressed and responsive to MITF." (PMID 25755924, 2015). "Hence, it could be concluded that EZH2 lowers the expression of CDKN1C by facilitating H3K27 trimethylation thereby facilitating melanoma cell viability and inhibiting oxidative stress and apoptosis of melanoma cells." (PMID 32308561, 2020). "Therefore, it could be concluded that silenced CDKN1C accelerated the viability of melanoma cells and prevented melanoma cells from oxidative stress and apoptosis while EZH2 knockdown aided to improve these functions by upregulating the expression of CDKN1C." (PMID 32308561, 2020). "However, the role of the miR-517a/CDKN1C/JNK signaling in melanoma still remains enigmatic." (PMID 32015692, 2020).
melanoma (continued). "PAX3, a transcription factor involved in melanocyte development, the receptor tyrosine kinase KIT, CDKN1C, and EPHA5 were upregulated in the melanoma compared to the atypical nevus, while NTRK3 and ROS1 were downregulated in the same comparison." (PMID 35052351, 2021). "Specifically, genes upregulated or downregulated in response to UV radiation involve CDKN1C, CDK2, COL11A1, KIT, and IGF1R, the majority of which are identified as differentially upregulated in melanoma versus atypical tumor or nevus." (PMID 35052351, 2021). "CDKN1C suppression following CITED1 overexpression has been shown to augment cell cycle progression and cell viability in melanoma cells." (PMID 32015692, 2020). "Further investigations into the interaction between miR-517a, CDKN1C and the JNK signaling pathway are still required to fully understand the specific mechanisms of miR-517a in melanoma." (PMID 32015692, 2020). "Overall, silencing miR-517a results in upregulated CDKN1C expression, and inhibited JNK signaling pathway activation, consequently promoting OS in melanoma cells." (PMID 32015692, 2020). "Through loss and gain of function experiments, the interactions between miR-517a, the cyclin dependent kinase inhibitor 1C (CDKN1C) and the c-Jun NH2-terminal kinase (JNK) signaling pathway, as well as their roles in OS of melanoma cells were identified." (PMID 32015692, 2020). "Collectively, our investigation displayed that the silencing of lncRNA GAS5 and CDKN1C or elevation of EZH2, accelerated the viability of melanoma cells while suppressed oxidative stress and apoptosis of melanoma cells." (PMID 32308561, 2020). "At the same time, upregulation of miR-517a could reverse the effects of CDKN1C, and the suppression of the JNK signaling pathway could promote OS in melanoma cells." (PMID 32015692, 2020).
omphalocele (10 papers, 2008 to 2025). Omphalocele is an embryopathy classified in the group of abdominal celosomias and is characterized by a large hernia of the abdominal wall, centered on the umbilical cord, in which the protruding viscera are protected by a sac. "Despite that most of the BWS features cannot be recognized in utero, a clear association was observed between IC2 LOM or CDKN1C mutations and omphalocele." (PMID 33810554, 2021). "Almost 90% of BWS patients with CDKN1C mutations have abdominal wall defects; in particular, omphalocele occurs in 71.6% of these cases." (PMID 29047350, 2017). "CDKN1C germline mutation is associated with increased incidence of exomphalos in BWS patients." (PMID 39319771, 2025). "Finally, CDKN1C mutations should be investigated, not only in all familial cases but also in sporadic cases presenting with omphalocele, both for research and diagnostic purposes." (PMID 26933465, 2016). "We can surmise that alterations of methylation levels at H19/IGF2:IG-DMR and KCNQ1OT1:TSS-DMR are not primarily associated to omphalocele, in our cohort; conversely, sequence variants at KCNQ1OT1:TSS-DMR and CDKN1C could represent susceptibility factors for the onset of isolated omphalocele." (PMID 29047350, 2017). "Midline defects such as exomphalos are also a cardinal feature of BWSp and are preferentially associated with reduced CDKN1C activity due to LOM KCNQ1OT1:TSS DMR or CDKN1C pathogenic variants." (PMID 35804856, 2022). "A well-defined (epi)genotype–phenotype correlation exists for omphalocele in BWS: it is caused by KCNQ1OT1:TSS-DMR loss of methylation in 86% of the cases, by CDKN1C mutation in 7%, and by UPD or H19/IGF2:IG-DMR gain of methylation in <10% of patients." (PMID 29047350, 2017). "Among the 19 cases with isolated omphalocele confirmed by follow-up, we observed a VUS (rs760463569) in CDKN1C in two cases (cases 16 and 20) and a rare variant of KCNQ1OT1:TSS-DMR in one case (case 19)." (PMID 29047350, 2017). "Instead, omphalocele is associated with IC2 LOM and CDKN1C mutations." (PMID 33810554, 2021). "BWS patients carrying CDKN1C mutations show a higher frequency of abdominal wall defects and omphalocele, whereas mice lacking of a maternal copy of the CDKN1C gene present a phenotype close to BWS with gastrointestinal tract abnormalities or exomphalos." (PMID 33101381, 2020). "Thus, omphalocele can be considered one of the major and most frequent clinical manifestations of BWS in cases of KCNQ1OT1:TSS-DMR loss of methylation or CDKN1C mutations." (PMID 29047350, 2017).
bladder cancer (9 papers, 2013 to 2025). "Further experiments suggested that CDKN1C might interact with RNF26 in bladder cancer cells." (PMID 34650035, 2021).
colorectal cancer (9 papers, 2011 to 2024). A primary or metastatic malignant neoplasm that affects the colon or rectum. "Furthermore, miR221/222 are reported to reduce p57Kip2 and p27Kip1 expression in hepatocarcinoma, in glioblastoma, in oral cancer, in colorectal cancer and B-cell malignancies EBV-associated Experimental data confirmed, at least in ovarian cancers, the specific action of miR-221/222 on CDKN1C." (PMID 29614816, 2018). "Previously, CDKN1C was identified as a tumor suppressor gene with decreased expression in various cancers including HCC, colorectal cancer and ovarian cancer." (PMID 33912215, 2021).
hydatidiform mole (9 papers, 2012 to 2025). A gestational trophoblastic disorder characterized by marked enlargement of the chorionic villi, hyperplasia of the villous trophoblastic cells and hydropic changes. "Among the markers used in differentiating the types of hydatidiform moles, p57, a maternally expressed and paternally imprinted protein encoded by CDKN1C (Cyclin Dependent Kinase Inhibitor 1C) gene on chromosome 11p15, emerged as the most robust discriminant." (PMID 41516022, 2025).
lung carcinoma (9 papers, 2011 to 2024). "Of note, it has been recently reported that CDKN1C induction blocks cell cycle progression of lung cancer cells." (PMID 38877560, 2024). "Chromatin immunoprecipitation (ChIP) assays with GR antibody validate the occupancy of glucocorticoid response element (GRE) in DEX sensitive lung cancer cell lines and is in close proximity (25KB) to the CDKN1C promoter of DEX sensitive cell lines." (PMID 37035141, 2023). "Here the authors show that glucocorticoid receptor activation induces cancer cell dormancy in lung cancer by regulating CDKN1C expression through a distal enhancer, and these dormant cells are addicted to IGF-1R signalling pathway." (PMID 34272384, 2021). "Taken together, our data show that direct GR-mediated upregulation of a single gene (CDKN1C) is required to initiate growth arrest in human lung cancer cell line models." (PMID 34272384, 2021). "Based on our results, we found potential and prospective clinical applications in GTSE1, NMU, FOS, and CDKN1C to act as prognostic markers in case of lung cancer." (PMID 32318583, 2020). "The computational techniques used here revealed that CDKN1C and FOS, which are down-regulated genes in lung cancer-positive patients, are closely associated with the compulsive situation and are responsible for the regulation number of biological comebacks." (PMID 32318583, 2020). "We strongly believe that GTSE1, NMU, FOS, and CDKN1C have potential and clinical application values to act as prognostic markers of lung cancer." (PMID 32318583, 2020). "The demonstration of the potential medical value of GTSE1, NMU, FOS, and CDKN1C in the prognosis of patients suffering from lung cancer was done by us in order to verify the levels of expression of FOS, CDKN1C, NMU, and GTSE1." (PMID 32318583, 2020). "Analyzing the mRNA expression microarrays showed FOS, GTSE1, CDKN1C, and NMU are greatly harbored by the patients of lung cancer and are observed to be differentially expressed (fold change ≥2.0) of these genes." (PMID 32318583, 2020). "Additionally, CDKN1C, GTSE1, NMU, and FOS are not correlated with one another, which indicates that every target can individually be cast off as a predictive marker for lung cancer." (PMID 32318583, 2020).
Silver-Russell syndrome (9 papers, 2011 to 2023). Silver-Russell syndrome is characterized by growth retardation with antenatal onset, characteristic facies and limb asymmetry. "Reminiscent of patients and mice with KDM5C mutations, microduplications of the region harboring Cdkn1c cause Silver-Russell Syndrome, characterized by growth retardation and short stature." (PMID 36831303, 2023). "Gain-of-function mutations in CDKN1C cause IMAGe and Silver-Russell syndrome, in which there is growth impairment." (PMID 35178492, 2022). "Mutations in CDKN1C causes the short stature condition IMAGe syndrome as well as being a rare cause of Silver-Russell Syndrome." (PMID 35178492, 2022). "Variants in CDKN1C associated with familial Silver-Russell syndrome or growth restriction but normal adrenal function were found towards the carboxyl-terminal region of this “hot-spot” domain (p.Arg279Leu, p.Arg281Ile)." (PMID 31497289, 2019). "In contrast, for several other genes (e.g., FGFR3 and NSD1) a loss of function is associated with tall stature (CATSHL syndrome and Sotos syndrome, respectively), and gain of function with short stature (FGFR3 and CDKN1C; Achondroplasia and Silver-Russell syndrome)." (PMID 34194391, 2021).